COL1A1 (collagen type I alpha 1 chain)
Diseases named in the same sentence as COL1A1 in open-access papers (continued):
Sharing a sentence is not in itself a finding about the gene and the disease.
dermatofibrosarcoma protuberans (continued). "Therefore, although some scholars prefer to refer to uterine tumors bearing COL1A1–PDGFB fusion as dermatofibrosarcoma in the uterus (considering the morphologic and IHC similarity), the nomenclature of uterine sarcoma with COL1A1–PDGFB fusion seems more appropriate." (PMID 36994196, 2023). "The frequency of fusions was also high in desmoplastic small round cell tumors (77.8%; 7 of 9 samples) and in dermatofibrosarcoma protuberans (100%; 4 of 4 samples), driven by EWSR1 or COL1A1 fusions, respectively." (PMID 40711866, 2025). "Pigmented dermatofibrosarcoma protuberans (DFSP): DFSP typically shows storiform spindle cell proliferation and is characterized by COL1A1: PDGFB fusion." (PMID 41409361, 2025). "Dermatofibrosarcoma Protuberans is a locally aggressive fibroblastic sarcoma of the dermis and subcutis, exhibiting CD34 positivity and COL1A1-PDGFB fusion." (PMID 41446319, 2025). "According to the previous literature, COL1A1–PDGFB gene fusion occurred mainly in soft tissue dermatofibrosarcoma protuberans and pediatric giant cell fibroblastoma, while it was rarely reported in the female genital tract." (PMID 36994196, 2023). "Roneparstat counteracted the autocrine loop induced by the COL1A1/PDGFB fusion oncogene, expressed in a human dermatofibrosarcoma protuberans primary culture and in NIH3T3COL1A1/PDGFB transfectants, inhibiting cell anchorage-independent growth and invasion." (PMID 27374103, 2016). "Reverse transcription PCR (RT-PCR) of the tumor tissue revealed gene fusion between exon 25 of COL1A1 and exon 2 of PDGFB; thus atrophic dermatofibrosarcoma protuberans was diagnosed." (PMID 26932148, 2016). "In dermatofibrosarcoma protuberans (DFSP), the growth factor platelet-derived growth factor B (PDGFB) is constitutively activated by the collagen, type I, alpha 1 (COL1A1) promoter in chromosome 17." (PMID 22665999, 2012). "The molecular pathogenesis of dermatofibrosarcoma protuberans (DFSP) involves distinctive rearrangement of chromosomes 17 and 22 leading to formation of the COL1A1-PDGFB fusion gene." (PMID 21559214, 2011). "The case of Patient No. 6, who developed vulvar dermatofibrosarcoma protuberans with COL1A1-PDGFB fusion, illustrates the potential utility of molecular characterization in guiding therapy." (PMID 40894946, 2025). "Dermatofibrosarcoma protuberans (DFSP) is a rare sarcoma, characterized by a COL1A1-PDGFB fusion." (PMID 40558511, 2025). "Noteworthy, dermatofibrosarcoma protuberans (DFSP), a rare STS subtype with a local infiltrative growth pattern, carries a COL1A1/PDGFB fusion-gene that is responsible for PDGFRβ autocrine activation and subsequent tumorigenesis." (PMID 32532153, 2020).
hepatocellular carcinoma (38 papers, 2014 to 2025). A malignant tumor that arises from hepatocytes. "COL1A1 overexpression has been reported across several malignancies, including breast, gastric, and hepatocellular carcinoma, and is associated with poor prognosis, metastasis, and drug resistance." (PMID 40860666, 2025). "Since an increased Col1a1 is usually associated with an enhanced fibrotic rate in hepatocellular carcinoma, we also decided to assess fibrosis of wild-type and DS livers by histopathology." (PMID 38942607, 2024). "In an effort to elucidate how MRPS31 loss-mediated mitoribosomal defects modulate hepatoma cell activity, we identified COL1A1, a component of type I collagen, as a key downstream effector molecule." (PMID 34772924, 2021). "In this study, we demonstrated that COL1A1 is produced by hepatoma cells with MRPS31 loss, and COL1A1/DDR signaling could enhance cell invasiveness by activating the ZEB1-mediated EMT, thereby contributing to HCC aggressiveness." (PMID 34772924, 2021). "On one hand, frequent promoter methylation of COL1A1 has been observed in renal cell carcinoma and hepatocellular carcinoma, and COL1A2 downregulation has been reported in melanoma, head and neck cancer, and bladder cancer." (PMID 41463322, 2025). "In hepatocellular carcinoma, overexpressed COL1A1 contributes to tumor progression and metastasis by modulating the tumor microenvironment." (PMID 38913913, 2024). "Collagen type I α1 (COL1A1), the major component of type I collagen, enhanced oncogenicity on hepatocellular carcinoma (HCC) cells." (PMID 38001428, 2023). "Knocking out COL1A1 can inhibit hepatocellular carcinoma cell migration and invasion by uncontrolled EMT in vitro." (PMID 35774273, 2022). "Study found that COL1A1 gene expression was markedly decreased in hepatocellular carcinoma tumor tissues (log2 ratio − 1.1) with a poor overall survival rate (P = 0.013)." (PMID 32641130, 2020). "On one hand, frequent promoter methylation of COL1A1 was detected in renal cell carcinoma and hepatocellular carcinoma, and COL1A2 was downregulated in melanoma, head and neck cancer, and bladder cancer." (PMID 27894325, 2016). "Previous studies on COL1A1 have primarily focused on human diseases and cancers, suggesting that the COL1A1 gene may serve as a biomarker and therapeutic target for hepatocellular carcinoma and metastasis." (PMID 40522964, 2025). "Hepatoma cell lines co-cultured with primary HSCs induced fibrotic activation by secreting fibrogenic factors, increasing the production of collagen type I alpha 1 (COL1A1) and TIMP metallopeptidase inhibitor 1 (TIMP1)." (PMID 41149169, 2025). "One of the few examples of COL1A1 downregulation in cancer was reported for hepatocellular carcinoma, where COL1A1 expression was significantly decreased in tumor tissue compared to adjacent normal tissue, with promoter hypermethylation identified as the silencing mechanism." (PMID 41469472, 2025). "In addition to COL1A1 and DDR1 knockdown, ZEB1 suppression significantly decreased SNU449 cell invasiveness, implying involvement of the COL1A1/DDR1/ZEB1 axis in hepatoma cell invasiveness." (PMID 34772924, 2021). "We also examined how hepatoma cell-derived COL1A1 regulates invasiveness." (PMID 34772924, 2021). "A recent study revealed that epigenetic down-regulation of COL1A1 mRNA expression might have a role as a prognostic biomarker of hepatocellular carcinoma." (PMID 28410203, 2017). "However, how COL1A1 expression is regulated in hepatoma cells and how COL1A1 modulates the cells’ activities remain unclear." (PMID 34772924, 2021). "COL1A1 confers a survival advantage and enhanced Hepatocellular Carcinoma (HCC) cell clonogenicity, tumorsphere formation and expression of stemness genes like SOX2, OCT4 and CD133." (PMID 33096662, 2020). "Furthermore, COL1A1 expression may represent an independent biomarker for the prediction of prognosis of hepatocellular carcinoma." (PMID 28775672, 2017).
hepatocellular carcinoma (continued). "ZIC5 promotes the malignant phenotype of hepatocellular carcinoma (HCC) by promoting β‐catenin signaling and COL1A1 expression." (PMID 40318167, 2025). "MRPS31 suppression enhanced hepatoma cell invasiveness by augmenting MMP7 and COL1A1 expression." (PMID 34772924, 2021).
colorectal cancer (36 papers, 2012 to 2025). A primary or metastatic malignant neoplasm that affects the colon or rectum. "HK3 expression correlates strongly with the expression of EMT‐associated genes such as ZEB2, SNAI2, TWIST1 and collagen type I alpha 1 chain (COL1A1) in human colorectal cancer specimens." (PMID 39030877, 2024). "As reported, the expression of COL1A1 was significantly upregulated in colorectal cancer tissues and cell lines, associated with metastasis, serosal invasion, lymph metastases and hematogenous metastases, indicating that COL1A1 may serve as an oncoprotein in colorectal cancer." (PMID 37805556, 2023). "In colorectal cancer, its interaction with circCSPP1 influences epithelial–mesenchymal transition through COL1A1." (PMID 40862743, 2025). "COL1A1 enhances the metastatic ability of colorectal cancer cells by affecting WNT/PCP signaling pathway." (PMID 39845977, 2024). "For example, COL1A1 has been reported to be linked with immune infiltrating cells, and RAB31 is expressed in CAFs, contributing to the malignant potential of colorectal cancer through the secretion of HGF in the tumor stroma." (PMID 38557819, 2024). "Numerous cancers, including colorectal cancer and medulloblastoma, have higher expression levels of COL1A1 and COL1A2." (PMID 37396945, 2023). "LOX has been implicated in the inhibition of β-catenin signaling in some cancers, and COL1A1 appears upregulated in colorectal cancer tissues and promotes metastasis via Wnt signaling." (PMID 34638991, 2021). "Lysyl oxidases (LOX), on the other hand, have been implicated in the inhibition of β-catenin signaling in some cancers, whereas the COL1A1 protein appears upregulated in colorectal cancer tissues and promotes metastasis via Wnt signaling." (PMID 34638991, 2021). "Research has shown that circCSPP1 acts as a promising therapeutic target by regulating the EMT process in colorectal carcinoma via activation of the circCSPP1/miR-193a-5p/COL1A1 axis." (PMID 33663510, 2021). "The key role of COL1A1 in esophageal cancer and colorectal cancer has been confirmed by studies." (PMID 39924716, 2024). "More importantly, we identified genes (e.g., Trim63, Fos, Col1a1, and Six2) that were regulated by high-intensity aerobic exercise, which adversely affected colorectal cancer development, and confirmed their effects in vitro using knockdown and overexpression systems." (PMID 35801156, 2022). "Besides, COL1A1 is upregulated in colorectal cancer (CRC) and promoted CRC cell migration via WNT/PCP signaling pathway." (PMID 34399848, 2021). "In addition, COL1A1 promotes cell migration in vitro and metastasis in colorectal cancer by regulating the WNT/PCP pathway." (PMID 33911160, 2021). "Previous researches have reported that COL1A1 could promote colorectal carcinoma by regulating the Wnt/PCP signaling pathway." (PMID 34598322, 2021). "COL1A1 could promote colorectal cancer metastasis by regulating the WNT/PCP pathway (Zhang, Wang, Zhang, Zhong, & Yang, 2018)." (PMID 31612481, 2020). "In conclusion, this finding indicates that circCSPP1 may act as a promising therapeutic target by regulating the EMT process in colorectal carcinoma via activation of the circCSPP1/miR-193a-5p/COL1A1 axis." (PMID 32612946, 2020). "In colorectal cancer (CRC) specifically, miR-133 has been reported to target multiple oncogenic factors including LASP1, TAGLN2, FSCN1, and COL1A1, thereby suppressing proliferation, migration, and invasion." (PMID 41300774, 2025). "Lastly, COL1A1 was able to activate the Wnt signalling pathway via RAC1 and promote migration in colorectal cancer." (PMID 33050615, 2020). "The aberrations found in this study (losses of TSC2, COL1A1, NOTCH1, MIR4673 and GNAS, and gains of MALAT1 and TALAM1) may serve as candidate biomarkers for early detection of colorectal cancer onset." (PMID 35887000, 2022).
colorectal cancer (continued). "The PPI networks indicate the RAB31, COL1A1, COL1A2, COL3A1, COL11A1, and VCAN as the most important protein network that likely to be connected and show betweenness among themselves to significantly promote the prognosis of colorectal cancer." (PMID 33597969, 2021). "On the other hand, COL1A1 and COL1A2 mRNA was upregulated in colorectal cancer and medulloblastoma." (PMID 27894325, 2016). "A previous study showed that expression of COL1A1 and COL1A2 was elevated in malignant colorectal endothelium cells, suggesting that these two proteins play a role in angiogenesis and formation of desmoplasia during colorectal cancer development." (PMID 25860484, 2015). "The result of the remained patients showed that, except for ITGB5, the other three genes COL1A1, FN1and SPP1were up-regulated in six cancer samples, and the COL3A1 was up-regulated in four cancer samples, suggesting the ECM-pathway genes are usually up-regulated in colorectal cancer." (PMID 22905095, 2012).
glioma (35 papers, 2010 to 2025). A benign or malignant brain and spinal cord tumor that arises from glial cells (astrocytes, oligodendrocytes, ependymal cells). "To evaluate the functional role of COL1A1 in oncostream formation we generated a Col1a1-deficient genetically engineered mouse glioma model." (PMID 35750880, 2022). "COL1A1 is one of the downstream targets of the glioma-associated oncogenes (GLI1 and GLI2), is involved in collagen deposition, and is associated with PDAC aggression." (PMID 36038612, 2022). "Inhibition of Col1a1 within glioma cells led to oncostream loss and reshaping of the highly aggressive phenotype of HGG." (PMID 35750880, 2022). "Indeed, the loss of Col1a1 expression from tumor cells disrupts the structural and functional characteristics of oncostreams, resulting in a complete loss of mesenchymal areas within gliomas and a reduction in glioma malignant behavior." (PMID 35750880, 2022). "Interestingly, the induction of this gene by ER stress was not affected by OASIS knock-down, suggesting that OASIS is not required for Col1a1 induction in glioma cells or that perhaps another ATF6 family isoform is able to compensate for OASIS loss allowing for Col1a1 induction in glioma cells." (PMID 23335989, 2013). "In the Glioma/NC group, 8 proteins (COL1A1, PRL, VWF, HBD, SF3B1, NME3, RRBP1, and CSRP1) were selected, with an AUC of 0.892 in the training set and 0.871 in the validation set (accuracy: 78.5%)." (PMID 39716938, 2025). "Deletion experiments demonstrated that COL1A1 is a critical determinant of oncostream formation, and glioma malignancy." (PMID 38384234, 2024). "These oncostreams, characterized by a unique molecular signature with a prominent overexpression of COL1A1, were directly correlated with glioma aggressiveness." (PMID 38384234, 2024). "Accordingly, the level of COL1A1 mRNA was high in glioma grade IV tissues by TCGA glioma dataset analysis." (PMID 37997289, 2024). "Col1a1 knockdown within glioma cells decreased oncostream formation, reprogramed glioma mesenchymal transformation, and remodeled the glioma TME, thus increasing animal survival." (PMID 35750880, 2022). "Analysis of the survival of patients with glioma expressing LOX or COL1A1 indicated that high expressions of these genes correlated with poor outcomes." (PMID 35908277, 2022). "The alignment analysis, Relative Position, and Pairwise correlation confirm the presence of not-aligned low-density cells compatible with single cell invasion patterns in gliomas with Col1a1 downregulation." (PMID 35750880, 2022). "Oncostreams are anatomically and molecularly distinctive, regulate glioma growth, display collective motion, and are regulated by the extracellular matrix, especially by COL1A1." (PMID 35750880, 2022). "Col1a1 is a central gene in the dynamic organization of glioma mesenchymal transformation, and a powerful regulator of glioma malignant behavior." (PMID 35750880, 2022). "In our mouse glioma models and in human gliomas, tumors with higher density of oncostreams also express higher levels of COL1A1." (PMID 35750880, 2022). "Previously, multi-cancer computational analysis found that within a mesenchymal transformation signature in different cancers including gliomas, COL1A1 was one of the top differentially expressed genes." (PMID 35750880, 2022). "In brief, these results reveal the potential of COL1A1 to recruit and activate immune cells in brain lower grade glioma." (PMID 35789341, 2022). "COL1A1 is a consistently differentially expressed gene in the glioma mesenchymal signature identified in malignant gliomas and in glioma stem cells as described in previous studies." (PMID 35750880, 2022). "Collagen1a1 (COL1A1) has been shown previously to be a major component of the extracellular matrix in different cancers, including glioma, and has been reported to promote tumor growth and invasion." (PMID 35750880, 2022).
glioma (continued). "COL1A1 is considered to be a marker of mesenchymal osteoblasts and is also defined as a glioma endothelial marker selectively expressed in microvessels." (PMID 35711921, 2022). "Genetic inhibition of Col1a1 within glioma cells depleted of Col1a1 from tumors, eliminated oncostream structures, reduced the glioma malignant phenotype, and prolonged animal survival." (PMID 35750880, 2022). "Overexpression or knockdown of COL1A1 was used to examine the effect on glioma cell proliferation of COL1A1." (PMID 36015199, 2022). "The double-immunofluorescence staining revealed that the co-expression of COL1A1 with IL-6 was found in WHO II-IV grade glioma tissues." (PMID 34034744, 2021). "qPCR analysis of a panel of glioma cell lines with variable Endo180 expression demonstrated substantial expression of both COL1A1 and COL1A2 transcripts in a subset of these cell lines as compared to the minor levels detected in normal brain." (PMID 20339555, 2010). "Additionally, COL1A1 protein has been reported to positively correlate with glioma invasion, and our data revealed significant overexpression of COL1A1 in both BrM and glioma plasma samples." (PMID 39716938, 2025). "Moreover, inhibition of Col1a1 within glioma cells led to downregulation of fibronectin expression, a mesenchymal associated extracellular matrix protein that is associated with a more aggressive phenotype." (PMID 35750880, 2022). "To determine whether the knockdown of Col1a1 in NPA gliomas alters the migration patterns observed for NPA gliomas we analyzed a NPAshCOL1A1 tumor by two-photon microscopy at a depth of 110 μm." (PMID 35750880, 2022). "To further analyze the effects of Col1a1 downregulation, we evaluated the histopathological features of glioma tumors, quantified oncostream density using deep learning analysis, and evaluated COL1A1 expression within glioma tissues." (PMID 35750880, 2022). "Moreover, TCGA-glioma data indicate that COL1A1 has differentially higher expression in GBM histological Grade IV." (PMID 35750880, 2022). "Some studies reported that density of COL1A1 inversely correlates with glioma patients’ prognosis." (PMID 35750880, 2022). "Our Kaplan–Meier analysis demonstrated that high expression of COL1A1, COL1A2, COL3A1, COL5A1, COL8A1, ELN, FN1 resulted in lower OS in all grade glioma patients, in turn causing poor prognosis." (PMID 36106447, 2022). "In addition, Col1a1 inhibition within glioma cells induced cell intrinsic and extrinsic changes in the TME." (PMID 35750880, 2022). "We propose that depletion of Col1a1 within glioma cells is a promising approach to reprogram mesenchymal transformation in glioma tumors, and could be harnessed as a therapeutic approach, and reduce the glioma malignant phenotype." (PMID 35750880, 2022). "Inhibiting Col1a1 within glioma cells is a potential therapeutic strategy to mitigate glioma mesenchymal transformation, intra-tumoral heterogeneity, and thus, potentially reduce deadly glioma invasion and continued growth." (PMID 35750880, 2022). "The expression of COL1A1 was associated with the grade of this tumor by the relative R package analysis, and the study indicated that expression of COL1A1 was a critical independent prognostic factor through multivariate analysis in patients of low-grade glioma." (PMID 35789341, 2022). "Then, we asked whether the knockdown of Col1a1 in NPA gliomas affects changes in the patterns of migration." (PMID 35750880, 2022). "Another studies have reported that COL1A1 is related to facilitate cell invasion in glioma." (PMID 33928021, 2021). "Our finding suggested that stimulating the Wnt/β-catenin signaling pathway could reduce the cell invasion of glioma cells by inhibiting the gene expression of Col1A1, LAMC3, and CD44." (PMID 28837560, 2017). "Therefore, it is important to further determine the role of COL1A1 in glioma growth and invasion." (PMID 35750880, 2022).